JAK2 (Janus kinase 2)
Diseases named in the same sentence as JAK2 in open-access papers (continued):
Sharing a sentence is not in itself a finding about the gene and the disease.
polycythemia vera (continued). "This latter patient had already been diagnosed with polycythemia vera (JAK2 V617F positive) years before PVT development." (PMID 32878264, 2020). "Ruxolitinib (RUX), a JAK1/JAK2 inhibitor, is approved for second-line therapy in patients with polycythemia vera (PV) who are resistant or intolerant to hydroxyurea." (PMID 33114733, 2020). "The somatic mutation JAK2-V617F is the most frequently observed driver mutation in BCR/ABL-negative MPNs, such as polycythemia vera (PV) and primary myelofibrosis (PMF)." (PMID 32050632, 2020). "Ruxolitinib is an FDA-approved JAK1/JAK2 inhibitor for treatment of myelofibrosis and polycythemia vera." (PMID 31781977, 2019). "In polycythemia vera, the STAT3 pathway correlates with poorer prognosis and is constitutively active due to the presence of the JAK2 V617F mutation." (PMID 31399589, 2019). "Allele burden of the JAK2 mutation also has an influence on disease phenotypes seen in polycythemia vera versus essential thrombocythemia, another related MPN in which about 50% of patients would harbor the JAK2 mutation." (PMID 31065022, 2019). "One was a very rare missense variant in JAK2 (p.E890K; MAF = 0.08%), which is the causative gene of polycythemia vera (MIM: 263300) and thrombocythemia-3 (MIM: 614521) and is activated by the binding of a growth hormone to a growth hormone receptor." (PMID 31562340, 2019). "JAK2 p.V617F is an activating mutation frequently detected in myeloproliferative disorders (MPN), specifically in > 90% of patients with polycythemia vera and in 60% of patients with essential thrombocythemia or idiopathic myelofibrosis." (PMID 29082853, 2017). "Most patients with MPN including polycythemia vera (PV), essential thrombocythemia (ET), and primary myelofibrosis (PMF) were found to have mutations in Janus kinase 2 gene (JAK2)." (PMID 25918716, 2015). "JAK2 was shown to be central to the erythropoietin-independent erythroid proliferation in polycythemia vera (PV)." (PMID 24252238, 2013). "A single acquired somatic mutation in the pseudokinase domain of JAK2, in the form of a substitution of Val for Phe at position 617, is at the base of >95% Polycythemia Vera (PV) patients and 50–60% of patients with Essential Thrombocythemia (ET) and Primitive Myelofibrosis (PMF)." (PMID 20585391, 2010). "The absence of a JAK2 mutation in our case prompted us to reconsider the diagnosis of polycythemia vera and investigate potential secondary causes." (PMID 39767963, 2024). "As a result of this study, it was suggested that JAK2-positive ET might present a clinical similarity to polycythemia vera." (PMID 35444868, 2022). "The result we obtained suggests that patients with JAK2, CALR, or MPL mutation-positive ET may have polycythemia vera." (PMID 35444868, 2022). "An 80-year-old female with a past medical history of Janus kinase 2 (JAK2) polycythemia vera, hypertension, transient ischemic attack presented to the emergency department with a one-day history of increasing, constant epigastric abdominal pain, which radiated to her back." (PMID 35891817, 2022). "A 59-year-old man was diagnosed with JAK2-positive polycythemia vera." (PMID 34631089, 2021). "Furthermore, pathologically deregulated erythropoiesis (polycythemia vera) is associated with an abnormal increase in the activation of the MAPK and PI3K/AKT pathways likely caused by the point mutation in JAK2 kinase." (PMID 34299300, 2021). "Importantly, in mice with human JAK2 V617F-induced polycythaemia vera, administration of fedratinib led to improvement in haematocrit, reduction in splenomegaly and prolonged survival." (PMID 32676568, 2020).
polycythemia vera (continued). "As CALR mutations are absent in polycythemia vera (PV; which is defined by the presence of JAK2 mutations), this most likely represents one end of the phenotypic spectrum of CALR-mutated MPN." (PMID 33312103, 2020). "Two male patients received higher doses (one patient with JAK2 positive polycythemia rubra vera (PRV) receiving 1 ml/kg) the other was young, unusually had no other comorbidities, had a very good exercise tolerance and was deemed “relatively fit” compared to the other subjects." (PMID 32207243, 2020). "When TET2 precedes JAK2, patients are more likely to present with polycythemia vera." (PMID 31784538, 2019). "The classic BCR-ABL1–negative MPNs include three different disorders, essential thrombocythemia (ET), polycythemia vera (PV), and primary myelofibrosis (PMF), and are caused by constitutive activation of the cytokine receptor/JAK2 pathway due to acquired somatic mutations in three major genes." (PMID 31346467, 2019). "It was established that several gains of function mutations (activation mutation) in JAK1, JAK2, and JAK3 are entirely responsible for hematopoietic disorders such as T and B cell acute lymphocytic leukemias, acute myeloid leukemia, polycythemia vera, essential thrombocytopenia, or Hodgkin Lymphoma." (PMID 29862290, 2018). "The diagnosis of polycythemia vera was supported by a positive JAK2 V617F analysis in 2013." (PMID 29685167, 2018). "When stratified by disease subtypes, the JAK2 46/1 haplotype and JAK2 rs12339666 were significantly associated with all three MPN subtypes, but TERT rs2736100 was only associated with essential thrombocythemia and polycythemia vera." (PMID 29100304, 2017). "The identification of a recurrent mutation in the tyrosine kinase Janus kinase 2 (JAK2V617F) in most patients with primary myelofibrosis (PMF), polycythemia vera (PV) and essential thrombocythemia (ET) suggest a potential common main cause of disease development." (PMID 26755644, 2016). "The Janus kinase 2 (JAK2)-V617F mutation and somatic mutations of JAK2 exon 12 constitutively activate JAK2 protein tyrosine kinase and these mutations are detected in almost all patients with polycythemia vera (PV)." (PMID 27504244, 2016). "Furthermore, we found that aUPD14q tends to arise before JAK2 V617F in essential thrombocythaemia but after V617F in polycythemia vera." (PMID 26114957, 2015). "Erythrocytosis is usually the main feature of polycythemia vera and is considered, with one of the JAK2 mutations, as a major criteria of this Ph negative MPN." (PMID 26187587, 2015). "To date, this case is the first description of a Breakpoint cluster region-Abelson murine leukemia viral oncogene homolog 1-positive chronic myeloid leukemia, presenting with erythrocytosis as the initial manifestation, and mimicking a Janus kinase 2 V617F-negative polycythemia vera." (PMID 26187587, 2015). "Clinical trials of polycythemia vera and essential thrombocythemia patients with lestaurtinib, a multikinase inhibitor of JAK1, JAK2, JAK3, FLT3 and TRKA/B/C has shown to modestly reduce JAK2-V617F allele burden and spleen size." (PMID 25656053, 2015). "The most intriguing feature of the present case was the presence of a marked erythrocitosis in a non-smoking patient, in the absence of polycythemia vera, JAK-2 mutations or other causes of primary polycythemia." (PMID 26537508, 2015). "Further analyses revealed the absence of any Janus kinase 2 mutation, thus excluding polycythemia vera." (PMID 26187587, 2015). "These mutations were revealed in the majority of ET and PMF patients with non-mutated JAK2 or MPL but not in polycythemia vera patients." (PMID 25386351, 2014). "The JAK2 V617F mutation has been observed in patients with Philadelphia chromosome-negative myeloproliferative neoplasms (Ph-MPNs), including polycythemia vera, essential thrombocythemia and idiopathic myelofibrosis." (PMID 25013507, 2014).
polycythemia vera (continued). "As such, Jak2 inhibitors may be more suited for the treatment of polycythemia vera and/or essential thrombocythemia, diseases which are characterized by expanded erythrocyte and thrombocyte lineages, respectively." (PMID 23544085, 2013). "Co-treatment of mTOR inhibitor with JAK2 inhibitor resulted in synergistic activity against the proliferation of JAK2V617F mutated cell lines and significantly reduced erythropoietin-independent colony growth in patients with polycythemia vera." (PMID 23382981, 2013). "Polycythemia vera was finally diagnosed by positive mutation of Janus kinase 2 and negative erythropoietin protein expression." (PMID 19946506, 2009). "Ruxolitinib is an oral Janus kinase (JAK) 1/JAK2 inhibitor first approved by the US Food and Drug Administration (FDA) in 2011 for the treatment of adults with intermediate or high-risk myelofibrosis (MF), including primary MF, post-polycythemia vera (PV) MF, and post-essential thrombocythemia MF." (PMID 37501130, 2023). "Polycythemia vera (PV) is a Philadelphia-negative chronic myeloproliferative neoplasm (MPN) characterized by the clonal expansion of an erythrocyte mass due to mutations in the JAK2 gene (V617F and exon 12) that cause hyperactivation of JAK-STAT signaling." (PMID 37509367, 2023). "Moreover, nine further CTEPH patients were reported to have polycythaemia vera albeit without genetic testing for the predisposing JAK2 pathogenic variant." (PMID 32397294, 2020). "Activating mutations in the pseudo-kinase domain of JAK2, such as JAK2V617F, lead to ligand-independent phosphorylation of JAK2 and downstream activation of signalling pathways in patients with polycythemia vera (PV)." (PMID 28732065, 2017). "In this context, polycythemia vera was suspected, but could not be confirmed by molecular biology analysis as she was negative for the JAK2 V617F mutation." (PMID 26187587, 2015). "The most well-known and widely used JAK2 inhibitor is ruxolitinib, which is FDA-approved for the treatment of myelofibrosis and polycythemia vera in adult populations." (PMID 40486651, 2025). "The classic BCR::ABL1-negative MPNs, polycythemia vera (PV), essential thrombocythemia (ET), and primary myelofibrosis (PMF), share an overactive JAK2-signaling as a common characteristic with the key driver genes JAK2, CALR, and MPL." (PMID 38835969, 2024). "Polycythemia vera was ruled out in this patient by negative JAK2 testing and normal erythropoietin levels." (PMID 40656289, 2025). "Similar to the JAKPOT score, our outcome of interest was detecting JAK2 mutant (primary) erythrocytosis rather than identifying patients with a formal WHO diagnosis of polycythemia vera." (PMID 40806795, 2025). "Among these, one of the HighE males had very high Hb (188 g/l), B-Eryt (6.27 × 10^12/l), and hematocrit (56%), necessitating further studies for erythropoietin and the JAK2 gene to rule out polycythemia vera." (PMID 40191210, 2025). "For example, while the JAK2 V617F mutation is the most common, particularly in MPN, a gain of function mutation in exon 12 of JAK2 is characteristic for polycythemia vera (PV) and is not commonly seen in primary myelofibrosis (PMF) or ET." (PMID 36810551, 2023). "In a very large series including patients with polycythemia vera and ET conducted in Italy, unlike other studies, JAK2 mutants were divided into heterozygous and homozygous mutants and their clinical implications were investigated." (PMID 35444868, 2022). "We have encountered a scenario in an NGS run, where one polycythemia vera (PV) case was negative for JAK2 V617F and a mycosis fungoides (MF) case in the same run was positive for JAK2 V617F." (PMID 36354687, 2022). "We examined the presence and distribution of phosphorylated (p) STAT5 in neoplastic cells in patients with MPN, including polycythemia vera (PV, n = 10), essential thrombocythemia (ET, n = 15) and primary myelofibrosis (PMF, n = 9), and in the JAK2 V617F-positive cell lines HEL and SET-2." (PMID 32326377, 2020).
polycythemia vera (continued). "In MPNs, JAK2 V617F is present in 50–60% of ET and PMF and 95% of polycythemia vera (PV)." (PMID 28955303, 2017). "Oxyhemoglobin dissociation curve (P50) was normal and Janus kinase 2 (JAK-2) mutation analysis was negative, ruling out polycythemia vera." (PMID 26537508, 2015). "An acquired transversion in JAK2 exon 14 (c.1849G>T) that is confined to hematopoietic cells and results in p.Val617Phe (JAK2V617F) is observed in approximately 90% of patients with polycythemia vera (PV), 50% of essential thrombocythemia (ET) cases and 50% of primary myelofibrosis (PMF) cases." (PMID 24475114, 2014). "In 2005, it was discovered that the activating mutation in Janus kinase 2 (JAK2), mostly at codon 617 (JAK2 V617F), is involved in the development of Ph-negative MPNs, including polycythemia vera (PV), essential thrombocythemia (ET), and primary myelofibrosis (PMF)." (PMID 38596359, 2024). "Eight weeks post-transplantation, the mice that received Jak2 p.V617F+Osm-/- BM developed no signs of polycythemia vera (PV), with red blood cell (RBC) count, hematocrit (HCT), and hemoglobin (HGB) values within the normal range, whereas the WT mice presented all the signs of disease." (PMID 41372120, 2025). "Non-CML MPNs such as polycythemia vera (PV), essential thrombocythemia (ET), or idiopathic myelofibrosis (IMF) display recurrent anomalies in the JAK2 tyrosine kinase that plays a critical role in mediating hematopoietic cytokine receptor signaling through the JAK/STAT pathway." (PMID 22007291, 2012).
breast cancer (326 papers, 2007 to 2026). A primary or metastatic malignant neoplasm involving the breast. "It has been shown that JAK2 mRNA expression is associated with favorable outcomes in breast cancer, particularly in recurrence-free survival, with a more pronounced protective effect in specific subtypes, such as triple-negative breast cancer." (PMID 40733498, 2025). "The EMT and metastasis of human breast cancer cells are positively linked with abnormal JAK2/STAT3 signal activation." (PMID 39079960, 2024). "Clinically, amplification of JAK-2 in breast cancer samples is highly linked to poor in overall survival, and low response to chemotherapy." (PMID 38827789, 2024). "In contrast, whole-genome sequencing analysis of 170 breast cancer patients demonstrated that distant metastasis from ER-positive patients causes JAK2 and STAT3 mutations, producing late inactivation of the formerly active cascade." (PMID 37834225, 2023). "In untreated women with TN breast cancer, an increase in JAK2 gene amplification has been reported and linked with chemotherapy resistance." (PMID 37628945, 2023). "We also observed reduced STAT3 signaling in metastases vs primary breast cancer samples in all four clinical cohorts, which concurs with reported inactivating JAK2 and STAT3 mutations in metastatic/relapse samples that are not observed in primary lesions." (PMID 37463901, 2023). "Long noncoding RNA associated with breast cancer brain metastasis (lnc-BM) is upregulated in metastatic cells where it induces the expression of CCL2 via the activation of the JAK2/STAT3 pathway." (PMID 35202089, 2022). "A recent study found that inactivating mutations in metastatic/relapsed breast cancer cells preferentially target the genes JAK2 and STAT3, and more in general, the JAK-STAT signaling pathway." (PMID 34568068, 2021). "In support of this, JAK2 expression was associated with a decreased risk of tumour recurrence in a large cohort of breast cancer patients." (PMID 27406745, 2016). "Significantly JAK2 has been implicated in interleukin (IL)-6-dependent breast cancer stem cell self-renewal, and in both IL-6- and IL-8-dependent growth of triple-negative breast cancers (TNBCs)." (PMID 26317899, 2015). "Other critical factors such as p-STAT5, p-STAT3, p-IGF-1R, Jak2 and Brk causing breast cancer were also suppressed by HSE." (PMID 22792362, 2012). "Loss of miR-375 has also been reported in gastric, liver and breast cancers, and a putative tumor suppressor role has been linked to a failure to repress the oncogenic miR-375 targets JAK2, YAP, PDK1 and RASD1." (PMID 22132151, 2011). "Additionally, we discovered trans correlations between specific gene alterations (FANCA, HRAS, PIK3CA, MAP2K1, JAK2) and the expression of 22 proteins, suggesting potential molecular mechanisms underlying breast cancer development and progression." (PMID 39844043, 2025). "It is well known that JAK2 activation is associated with HER2 positivity in breast cancer." (PMID 39739128, 2024). "In clinical situations, JAK2 amplification in tumor samples is strongly associated with poor recurrence-free survival, poor overall survival, and low responsiveness to neoadjuvant chemotherapy in breast cancer patients." (PMID 35269680, 2022). "Furthermore, in primary breast cancer, Jak2 mRNA has a positive association with both LepR (R = 0.61) and FGFR1 mRNA (R = 0.49)." (PMID 33019728, 2020). "The JAK2/STAT3 axis has been implicated in the enhanced breast cancer cell metastasis." (PMID 31315632, 2019). "Likewise, janus kinase 2 (Jak2) mRNA expression in breast cancer cells was associated with increased numbers of tumor infiltrating leukocytes and better prognosis." (PMID 28100240, 2017). "Additionally, the JAK2/STAT3/IL6 pathway has been shown to be required for the growth of CD44-CD24+ breast cancer cells, cell surface markers believed to be associated with breast TICs." (PMID 27764181, 2016).